SFTPD (surfactant protein D)
Diseases named in the same sentence as SFTPD in open-access papers (continued):
Sharing a sentence is not in itself a finding about the gene and the disease.
lung adenocarcinoma (3 papers, 2018 to 2024). A carcinoma that arises from the lung and is characterized by the presence of malignant glandular epithelial cells. "The low expression of SFTPD in H1299 cells and TCGA samples indicates that SFTPD may be a protective factor in lung adenocarcinoma patients but is inhibited in tumor tissue." (PMID 34539740, 2021).
pancreatic cancer (3 papers, 2018 to 2019). "Human surfactant protein D induces apoptosis in pancreatic cancer cell lines via Fas-mediated pathway." (PMID 30792708, 2019). "In this study, we show that a recombinant fragment of human surfactant protein D (rfhSP-D) induces apoptosis in a range of pancreatic cancer cell lines." (PMID 29915574, 2018).
inflammatory bowel disease (2 papers, 2021). A spectrum of small and large bowel inflammatory diseases of unknown etiology. "Deleted in malignant brain tumours 1 protein (DMBT1) and surfactant protein D (SFTPD) are antimicrobial peptides previously linked to inflammatory bowel disease (IBD) susceptibility." (PMID 34828659, 2021).
newborn respiratory distress syndrome (2 papers, 2018 to 2025). A condition beginning in the first day of life that results from inadequate surfactant production, causing increased work of breathing and impaired gas exchange. "Current surfactant therapies for respiratory distress syndrome do not include surfactant protein D (SP-D), which is involved in regular surfactant lipid structure and lipid recycling." (PMID 41018057, 2025).
systemic scleroderma (2 papers, 2020 to 2024). "The latest studies focused on glycoprotein Krebs von den Lungen-6, surfactant protein-D, chemokine ligand 18 and dipeptidylpeptidase 4 as potential biomarkers of skin fibrosis in systemic scleroderma." (PMID 33214624, 2020).
allergic asthma (1 paper, 2023). A asthma with a basis in a pathological type I hypersensitivity reaction. "Surfactant protein D, a pattern-recognition molecule belonging to the collectin family, was reported to correlate with the development of respiratory diseases, including allergic asthma and BPD." (PMID 36857022, 2023).
atherosclerosis (1 paper, 2018). A disease characterized by the build-up of fatty material and calcium deposition in the arterial wall resulting in partial or complete occlusion of the arterial lumen. "Recently obtained data indicated nominal associations between SFTPD coding variants, including the Met11Thr polymorphism, and subclinical atherosclerosis, and demonstrated that the direction of the effects was dependent on tobacco smoking, but independent of circulating SP-D levels." (PMID 29473039, 2018).
bronchiolitis (1 paper, 2013). Inflammation of the bronchioles characterized by swelling of the bronchioles and mucus accumulation. "Genetic polymorphisms of SFTPA (surfactant protein A), SFTPD (surfactant protein D), TLR (toll like receptor) 4, TNF (tumor necrosis factor), IL4 (interleukin 4), IL9, IL10, IL8, IL13, IL4RA, and CCL5 have been reportedly associated with a susceptibility to RSV-induced bronchiolitis." (PMID 23986756, 2013).
bronchioloalveolar carcinoma (1 paper, 2025). A well or moderately differentiated morphologic variant of lung adenocarcinoma characterized by tumor growth along the alveolar structures without stromal, vascular, or pleural invasion. "The second potential explanation for these results may lie in T-cadherin’s ability to downregulate the secretion of surfactant protein D (SP-D), as previously demonstrated in human lung A549 cells (a human bronchioloalveolar carcinoma cell line with properties of type-II alveolar cells)." (PMID 40109358, 2025).
Crohn disease (1 paper, 2018). A gastrointestinal disorder characterized by chronic inflammation involving all layers of the intestinal wall, noncaseating granulomas affecting the intestinal wall and regional lymph nodes, and transmural fibrosis. "SFTPD (SP-D gene) polymorphisms increase the susceptibility to chronic and infectious lung diseases, pneumococcal lung disease, emphysema, tuberculosis, Crohn’s disease, and ulcerative colitis." (PMID 29915574, 2018).
dry eye (1 paper, 2020). "In a previous study, we showed that experimentally-induced dry eye (EDE) did not increase murine corneal susceptibility to colonization by deliberately-inoculated Pseudomonas aeruginosa, and that corneal defense under EDE conditions involved surfactant protein D (SP-D)." (PMID 32470039, 2020).
Ebola (1 paper, 2018). "A screening of Ebola glycoprotein (GP)-collectins interactions revealed the specific interaction of human surfactant protein D (hSP-D), a lectin expressed in lung and liver, two compartments where Ebola was found in vivo." (PMID 30587835, 2018).
endometrioid adenocarcinoma (1 paper, 2019). An adenocarcinoma characterized by the presence of malignant glandular epithelial cells resembling endometrial cells. "The Hendrix dataset demonstrated that SP-D (SFTPD) is expressed in a wide range of ovarian cancers such as: clear cell adenocarcinoma (n = 8), endometrioid adenocarcinoma (n = 37), mucinous adenocarcinoma (n = 13), serous adenocarcinoma (n = 41) and normal ovaries (n = 4)." (PMID 31338320, 2019).
endothelial dysfunction (1 paper, 2025). In vascular diseases, endothelial dysfunction is a systemic pathological state of the endothelium (the inner lining of blood vessels) and can be broadly defined as an imbalance between vasodilating and vasoconstricting substances produced by (or acting on) the endothelium. "Furthermore, our findings revealed that biomarkers reflecting fibroproliferative processes (VEGF, uPAR, galectin-3, E-selectin, and surfactant protein D), endothelial dysfunction (ANG-2, PECAM-1, and ICAM-1), and D-dimer were also associated with increased mortality risk." (PMID 41217548, 2025).
Impaired glucose tolerance (1 paper, 2013). An abnormal resistance to glucose, i.e., a reduction in the ability to maintain glucose levels in the blood stream within normal limits following oral or intravenous administration of glucose. "The frequency of the G allele in the chromosome 10 at the position rs721917 NC_000010.10: g.81706324A>G (Contig position) of the surfactant protein-D (SP-D) gene was lower in subjects with impaired glucose tolerance and T2D (IGT)." (PMID 23577114, 2013).
liver cancer (1 paper, 2025). An epithelial or non-epithelial malignant neoplasm that arises from the liver. "The MR results revealed significant associations between three FODMAP dietary components, cheese, cereal, and dried fruit intake, and six liver cancer‐related proteins (ANXA2, SFTPD, TGFB3, EPOR, ELANE, and C3)." (PMID 40895144, 2025).
pneumonitis (1 paper, 2024). An inflammatory process affecting the lung parenchyma. "Severe pneumonitis was more frequent in patients with squamous cell carcinoma, fibrosis, low diffusing capacity for carbon monoxide (%DLCO), and high surfactant protein D (SP‐D) level." (PMID 38828610, 2024).
radiation pneumonitis (1 paper, 2017). Inflammation of the lung due to harmful effects of ionizing or non-ionizing radiation. "Radiation pneumonitis post-treatment progression correlated with dosimetric factors of the lungs (V5, V10) and a low pre-treatment serum surfactant protein-D." (PMID 28865463, 2017).
respiratory syncytial virus infections (1 paper, 2011). "SFTPD polymorphisms in humans have been associated with surfactant protein D assembly, function, and concentration, as well as severe respiratory syncytial virus infections, a known precipitating factor for OM." (PMID 21857919, 2011).
scleroderma (1 paper, 2023). Scleroderma is a rare autoimmune connective tissue disorder characterized by abnormal hardening of the skin and, sometimes, other organs. "Surfactant Protein D (SP-D) and Krebs von den Lungen-6 (KL-6) are glycoproteins secreted by type II pneumocytes that can be used as markers of disease progression and also to signify the extent of lung involvement in scleroderma." (PMID 37035331, 2023).
serous cystadenocarcinoma (1 paper, 2018). A malignant serous cystic neoplasm usually involving the ovary or the pancreas. "We observed a lower expression of SFTPD mRNA expression in normal ovary than in serous cystadenocarcinoma (p < 0.05)." (PMID 30127783, 2018). "The Kaplan–Meier plotter data, derived from stage-1 and -2 patients, showed a negative ratio between SFTPD expression and either overall or progression-free survival rates of patients with serous cystadenocarcinoma (p < 0.05)." (PMID 30127783, 2018).
infection (15 papers, 2005 to 2026). The state of being infected such as from the introduction of a foreign agent such as serum, vaccine, antigenic substance or organism. "A previous study found that A. fumigatus conidia infections caused a decrease in SFTPD expression." (PMID 34204112, 2021). "Host gene variants involved in trafficking (FYCO1 and RAB7A) and immune signaling (FOXA2, SFTPD, STAT3, and TET2) were associated with differential infection profiles." (PMID 41683583, 2026). "The pulmonary surface is protected by a surfactant layer enriched with proteins such as surfactant protein A (SP-A) and surfactant protein D (SP-D), which play critical roles in preventing infection and modulating immune responses." (PMID 41515964, 2025). "Variants in other genes involved in IFN signaling and more recently in lung function (i.e., MUC5B and SFTPD) SNPs were found to be related to infection severity." (PMID 37515136, 2023). "We determined the location within the promoter region of SFTPD that exhibits a response to conidia infection." (PMID 34204112, 2021). "We investigated the transcription factor and promoter region of SFTPD, which is activated during the infection process in conidia-treated cells." (PMID 34204112, 2021). "Multiple soluble C-type lectins, such as mannose-binding lectin (MBL), surfactant protein D (SP-D), and collectin kidney 1, possess neutralizing activity against influenza virus during infection (28, –, 30)." (PMID 27795434, 2017). "For instance, surfactant protein D (SP-D) present in tear fluid has been shown to take part in clearing P. aeruginosa from the murine ocular surface, while exogenous vasoactive intestinal peptide regulates expression of other proteins involved in infection." (PMID 33182687, 2020). "Infection led to downregulation of surfactant genes (SFTPA1, SFTPC, SFTPD), cellular transition from functional ATIIs to proliferative ATIIs (mitotic), and PATS-like states, mimicking injury-induced alveolar regeneration pathways overserved in vivo." (PMID 41502560, 2025). "Surfactant protein D (SP-D) has particularly important roles in restricting IAV replication and limiting the severity of inflammatory responses during the first several days of infection." (PMID 17280604, 2007). "In summary, the absence of lung surfactant protein D increases the persistence of pneumococcal colonisation and infection in the upper and lower respiratory tract, as well as leading to earlier onset and increased levels of bacteraemia." (PMID 16255775, 2005). "Prophylactic treatment of GG was found to significantly inhibit the expression of surfactant protein D (sftp-D) and plasminogen activator inhibitor-1 (PAI-1) while reducing the expression of mucin-1 (muc1) and exotoxin to 1.5- to 2-fold as compared to the infection control." (PMID 36238303, 2022).
cancer (12 papers, 2018 to 2026). A tumor composed of atypical neoplastic, often pleomorphic cells that invade other tissues. "CONCLUSION: Together, these findings point to an oncogenic role for lnc-HNRNPUL2 in CRC, which acts via miR-335-5p suppression, followed by a decrease in SFTPD mRNA that is involved in immune surveillance against several cancers." (PMID 41882606, 2026). "Surfactant protein D (SP-D), a pattern recognition molecule, is emerging as a potent anti-tumoural innate immune defense molecule in a range of cancers." (PMID 35874783, 2022). "Surfactant protein-D (SP-D), a member of the collectin family has been shown to induce apoptosis in cancer cells." (PMID 33542717, 2021). "Similar to the overall transcriptional profile of cancer cells in the GG component samples, surfactant-associated proteins (SFTPA1, SFTPA2, SFTPB, SFTPC, and SFTPD) were highly expressed, and the expression level was higher than that of other cancer cell subclusters of the GG component samples." (PMID 35874770, 2022). "OC-X treatments also caused surge upregulation of several important biomarkers within each cancer progression stage, including UCP1, NOSTRIN, SCGB3A1, ENG, EPAS1, SFTPD, and BMP4." (PMID 34069906, 2021). "In comparison to ciliated, Club/Clara cells, pulmonary alveolar type 1 (AT1) and pulmonary alveolar type 2 (AT2), the EGFRex19 cancer cell cluster was characterized by high expression of NPC2 and surfactant genes SFTPB, SFTPC, and SFTPD." (PMID 33712615, 2021). "To identify the tumor cells and non-tumor lung cells, we first mapped the expression of six genes (FOLR1, AGR3, and SFTPD for normal hung lung cells, and EPCAM, MDK, and SOX4 for cancer cells) to each cluster to identify the cell types in our study." (PMID 32549766, 2020).
tumor (8 papers, 2017 to 2024). "Following the overexpression of KCNE1, NPC2, and SFTPD, M0 macrophages exhibited a substantial reduction in the polarization of M2 macrophages as well as the quantity of tumor-promoting cytokines that were produced by the cells." (PMID 38509982, 2024). "Finally, we characterized the expression of three LSAGs (KCNE1, NPC2, and SFTPD) in malignant lung epithelium and assessed their impact on tumor malignancy related phenotypes." (PMID 38509982, 2024).
bacterial infections (2 papers, 2021 to 2025). "Surfactant protein-D (SFTPD) and mannose-binding lectin (MBL) play a critical role in innate immunity and response to bacterial infections." (PMID 33679736, 2021).
inflammation (2 papers, 2006 to 2024). Aberrant reaction of the microcirculation characterized by movement of fluid and leukocytes from the blood into extravascular tissues. "Surfactant protein-D is a protective protein in pulmonary inflammation, which increases in serum, particularly in the context of mild and severe neutrophilic asthma." (PMID 39682469, 2024).
infectious disease (1 paper, 2018). A disorder directly resulting from the presence and activity of a microbial, viral, or parasitic agent in humans. "CGN1 is the first gene in the bovine collectin locus, a 260-kb region on chromosome 28 which includes the CL46, CL43, SFTPD, MBL1, and SFTPA1 genes, and several of these genes have been implicated in infectious disease susceptibility." (PMID 29744529, 2018).
SFTPD also shares sentences with these, for which no sentence is quoted: acute respiratory distress syndrome (7 papers); pneumonia (4); rheumatoid arthritis (4); Type 2 Diabetes (4); acute respiratory failure (3); breast carcinoma (3); influenza (3); bronchopulmonary dysplasia (2); Cardiovascular Disease (2); colorectal cancer (2); diabetes mellitus (2); eosinophilia (2); non-small cell lung carcinoma (2); osteoarthritis (2); pneumoconiosis (2); prostate carcinoma (2); Respiratory Diseases (2); respiratory infection (2); RSV bronchiolitis (2); silicosis (2); acute kidney injury (1); adenocarcinoma (1); AIDS (1); alveolitis (1); Aphthous Stomatitis (1); asbestosis (1); aspergillosis (1); Autoimmunity (1); bacteremia (1); bacterial pneumonia (1).
A further 44 diseases each share a sentence with SFTPD in 1 paper.